TINCR (TINCR ubiquitin domain containing)
Diseases named in the same sentence as TINCR in open-access papers (continued):
Sharing a sentence is not in itself a finding about the gene and the disease.
melanoma (6 papers, 2017 to 2025). A malignant, usually aggressive tumor composed of atypical, neoplastic melanocytes. "In addition to increased proliferation and invasion, TINCR underexpression, characteristic of melanoma cells, was associated with a significantly reduced percentage of apoptotic cells (p < 0.001)." (PMID 37629553, 2023). "However, the association of TINCR expression with melanoma clinic-pathological features and prognosis is still missing." (PMID 35159386, 2022). "This study ultimately demonstrated reduced levels of lncRNA TINCR in melanoma, resulting in reduced apoptosis mediated by the regulation of LATS1 mRNA expression." (PMID 37629553, 2023). "The authors found significant downregulation of TINCR expression in melanoma, with advanced stages demonstrating greater downregulation." (PMID 37629553, 2023). "We showed that TINCR is mildly expressed in melanocytes and upregulated in primary melanomas, where it functions as a barrier to the invasive phenotype switch." (PMID 35159386, 2022). "Restoration of high-level expression of TINCR in metastatic melanomas reverts the invasive phenotype, thus demonstrating the direct involvement of TINCR in the metastatic process." (PMID 35159386, 2022). "TINCR downregulation inhibits melanoma development in vivo by suppressing the ATF4-CHOP pathway and activating the Hippo pathway." (PMID 35159386, 2022). "TINCR is highly expressed in primary melanomas, is downregulated in metastatic melanomas, and is required to maintain the proliferative cell state." (PMID 35159386, 2022). "Recently, we discovered that the lncRNA TINCR plays a novel role in drug resistance in melanoma patients." (PMID 35159386, 2022). "Importantly, overexpression of TINCR in melanoma patient-derived xenografts partially reduced melanoma cell invasiveness and sensitized cells to the MEK1/2 inhibitor trametinib." (PMID 35159386, 2022). "We identified TINCR lncRNA as a suppressor of melanoma invasion and metastasis formation." (PMID 35159386, 2022). "Consistently, metastatic melanomas display very low levels of TINCR RNA." (PMID 35159386, 2022). "This suggests that TINCR might play a critical regulatory role in melanoma formation and metastasis." (PMID 28225791, 2017). "However, only SPRY4-IT1 and TINCR have been reported to participate in melanoma." (PMID 28225791, 2017). "TINCR expression prevents translational reprogramming, activation of ATF4, and stress response in melanoma." (PMID 35159386, 2022). "On the other hand, TINCR acts upstream of MITF to repress its expression and block the spread of melanoma whilst SAMMSON is frequently co-amplified with MITF in melanoma and is essential for melanoma cell proliferation and survival." (PMID 41336739, 2025). "On contrary, lncRNA TINCR was depleted under the normal oxygen condition, so as to mediate global translational reprogramming and increased proteins synthesis of ATF4 and other integrated stress response, leading to melanoma metastasis." (PMID 36541918, 2022). "Even though TINCR regulation is not well-characterized, it is one of the few examples of ncRNAs indirectly regulating melanoma transcriptional states." (PMID 36497341, 2022). "On the other hand, lncRNA TINCR is a negative translation regulator of the integrated stress response (ISR) transcription factor ATF4 through the direct binding of mRNAs driving the mesenchymal-like melanoma phenotype." (PMID 36497341, 2022).
prostate carcinoma (6 papers, 2015 to 2023). A carcinoma that arises from epithelial cells of the prostate gland. "TINCR acts as a tumor suppressor in prostate cancer and inhibits tumor metastasis." (PMID 37051356, 2023). "lncRNA TINCR suppresses the transcription and translation of TRIP13 in prostate cancer cells." (PMID 36157234, 2022).
squamous cell carcinoma (6 papers, 2017 to 2024). A carcinoma arising from squamous epithelial cells. "Moreover, we demonstrate that expression of the TINCR protein can impair tumor growth in squamous cell carcinoma cell lines and document that loss of TINCR protein expression is associated with poor prognosis in metastatic cutaneous SCC." (PMID 36899004, 2023). "Following these findings, we explored the presence of genetic alterations involving the TINCR locus in squamous cell carcinoma clinical samples." (PMID 36899004, 2023). "Altogether, these results demonstrate a role for TINCR as protein coding tumor suppressor gene recurrently lost in squamous cell carcinomas." (PMID 36899004, 2023). "Genetically, copy number alteration analysis revealed highly prevalent heterozygous chromosomal losses encompassing the TINCR locus across head and neck (~28%), lung (~39%), esophageal (~38%), and cervical (~32%) squamous cell carcinomas in TCGA cohorts." (PMID 36899004, 2023). "In human squamous cell carcinoma specimens, the expression of TINCR was down-regulated, which is consistent with the decrease in the differentiation of squamous cell carcinoma." (PMID 32185124, 2020). "TINCR, a lncRNA isolated from human well differentiated somatic tissues, controls epidermal differentiation and is downregulated in squamous cell carcinoma." (PMID 28548932, 2017). "Here we report the identification of TINCR as a tumor suppressor in squamous cell carcinoma (SCC)." (PMID 36899004, 2023). "Interestingly, recent studies showed that although TINCR is not a noncoding RNA, it encodes a ubiquitin-like protein that promotes keratinocyte proliferation in wound healing and suppresses tumor growth in squamous cell carcinoma." (PMID 38468869, 2024). "In addition, aberrant TINCR expression has also been demonstrated in human squamous cell carcinoma." (PMID 28546230, 2017). "In particular, it will be important to explore the potential role of TINCR downstream of proliferation-driving oncogenic (RAS) and tissue organization and differentiation tumor suppressor (NOTCH) pathways commonly disrupted in squamous cell carcinoma." (PMID 36899004, 2023). "Moreover, squamous carcinoma cell lines show no detectable TINCR expression and lentiviral expression of the TINCR coding mRNA sequences resulted in impaired cell growth." (PMID 36899004, 2023).
lymph node metastasis (5 papers, 2017 to 2023). "qRT-PCR analyses validated down-regulation of TINCR in tumor tissues compared with paired NATs, and its expression was closely correlated with pathological differentiation and lymph node metastasis in patients with OSCC." (PMID 33732637, 2021). "Here, we showed that TINCR was upregulated in CRC tissues and cells, and TINCR overexpression was closely associated with differentiation, TNM stage, Lymph node metastasis and poor OS." (PMID 30853664, 2019). "In addition, lymph node metastasis and a tumor thickness of less than 6 mm was correlated with negative expression of TINCR protein." (PMID 36899004, 2023).
liver cancer (4 papers, 2022 to 2023). An epithelial or non-epithelial malignant neoplasm that arises from the liver. "Results of previous studies demonstrated that the expression levels of TINCR in gastrointestinal tumor tissues were higher than those in adjacent normal tissues (ANTs) and the high expression of TINCR is associated with the prognosis and lymphatic metastasis of patients with liver cancer." (PMID 37051356, 2023). "We found that knocking down lncRNA TINCR (shRNA-TINCR-1 and shRNA-TINCR-2) increased significantly liver cancer cell apoptosis as compared to the control group (shRNA-control)." (PMID 36157234, 2022). "By controlling the miR-375/ATG7 axis, the lncRNA TINCR impacts the proliferation and invasion of liver cancer cells." (PMID 36157234, 2022). "Overexpression of lncRNA TINCR greatly enhances liver cancer cell proliferation, as shown by tests in vivo using nude mice." (PMID 36157234, 2022). "The findings demonstrated that liver cancer cell proliferation was dramatically suppressed when lncRNA TINCR was knocked down (shRNA-TINCR-1 and shRNA-TINCR-2)." (PMID 36157234, 2022). "Cell function tests show that overexpression of lncRNA TINCR greatly boosted the proliferation, colony formation, invasion, and inhibition of apoptosis of liver cancer cells, whereas knockdown of lncRNA TINCR had the opposite effect." (PMID 36157234, 2022). "Liver cancer cell proliferation was shown to be significantly elevated when lncRNA TINCR was overexpressed compared to the vector-control group." (PMID 36157234, 2022). "To further examine the impact of lncRNA TINCR overexpression on the proliferation and invasion of liver cancer SMMC-7721 cells, we used CCK-8 to measure cell proliferation caused by lncRNA TINCR overexpression." (PMID 36157234, 2022). "In conclusion, TINCR reduces miR-375 expression in liver cancer cells, which lowers ATG7 to limit cell proliferation and invasion." (PMID 36157234, 2022). "Overall, our work provided evidence that the lncRNA TINCR controls the growth and invasion of liver cancer cells through the miR-375/ATG7 signaling pathway." (PMID 36157234, 2022). "Liver cancer cells responded differently to knockdown of the lncRNA TINCR compared to overexpression in terms of proliferation, colony formation, and invasion." (PMID 36157234, 2022). "According to the results of this investigation, lncRNA TINCR is substantially expressed in liver cancer tissues and cells." (PMID 36157234, 2022). "Overexpression of lncRNA TINCR resulted in significantly more clones of liver cancer cells forming compared to the vector-control group in a clonogenic assay." (PMID 36157234, 2022). "miR-375 mimics reduce the stimulatory impact of lncRNA TINCR on liver cancer cell proliferation and invasion, while transfection of a miR-375 inhibitor significantly reverts this effect." (PMID 36157234, 2022). "Overexpression of lncRNA TINCR was shown to significantly increase liver cancer cell proliferation in vivo, in comparison to the control group." (PMID 36157234, 2022). "Western blotting was used to investigate the role of miR-375 in the regulation of ATG7 expression by lncRNA TINCR in liver cancer cells." (PMID 36157234, 2022). "Transfection of miR-375 mimics greatly inhibited the inhibitory effect of lncRNA TINCR knockdown on the invasion and proliferation, whereas transfection of miR-375 inhibitor considerably reverses this effect on liver cancer cells." (PMID 36157234, 2022). "Knockdown of lncRNA TINCR substantially suppressed colony formation in liver cancer cells compared to the blank control group (shRNA-control) as shown by the clonogenic test." (PMID 36157234, 2022). "To further understand the molecular mechanism by which lncRNA TINCR plays a role in liver cancer cells, we used RNA-FISH to map its distribution inside the tumor cells." (PMID 36157234, 2022). "TINCR knockdown (shRNA-TINCR-1) HepG2 liver cancer cells proliferated and invaded less than the control group (shRNA-control)." (PMID 36157234, 2022).
liver cancer (continued). "Transwell assays showed that knocking down lncRNA TINCR reduced the capacity of liver cancer cells to invade." (PMID 36157234, 2022). "Overexpressing lncRNA TINCR increased liver cancer cell proliferation in vivo." (PMID 36157234, 2022). "The lncRNA TINCR has been found in liver cancer tissues, although its role and molecular mechanism are unknown." (PMID 36157234, 2022). "Furthermore, in vivo nude mouse assay demonstrated that overexpression of lncRNA TINCR inhibited liver cancer cell growth." (PMID 36157234, 2022). "Overexpression of lncRNA TINCR significantly stimulated liver cancer cell proliferation in vivo." (PMID 36157234, 2022). "Transwell was used to determine the impact of lncRNA TINCR on the invasion capacity of liver cancer cells, and the findings indicated that lncRNA TINCR overexpression increased the invasion ability of liver cancer cells in comparison to the vector-control group." (PMID 36157234, 2022). "Moreover, TINCR is overexpressed in liver cancer, highlighting that TINCR may act as a promoter of liver cancer progression." (PMID 37051356, 2023). "Overexpression of lncRNA TINCR induced apoptosis in SMMC-7721 cells, a liver cancer cell line, while it significantly suppressed apoptosis of liver cancer cells, as compared to the vector-control group." (PMID 36157234, 2022). "TINCR sponges miR-218-5p to prevent miR-218-5p from targeting DDX5, thus promoting the progression of liver cancer." (PMID 35992805, 2022). "Experiments on cell function showed that lncRNA TINCR regulates miR-375/ATG7, which in turn influences liver cancer cell proliferation and invasion." (PMID 36157234, 2022). "Subcutaneous injections of SMMC-7721 cells (a liver cancer cell line that overexpresses lncRNA TINCR) or control cells (without expressing TINCR) were made into NOD/SCID mice." (PMID 36157234, 2022). "Luciferase reporter and Western blotting showed that lncRNA TINCR regulates the expression of ATG7 through miR-375, and the rescue experiment proved that lncRNA TINCR controls the invasion and proliferation of liver cancer cells via the miR-375/ATG7 signaling pathway." (PMID 36157234, 2022). "Using RT-PCR, TINCR expression was evaluated in liver cancer cell lines (Hep2, Hep3B, SMMC-7721, Hub7, and H-97) and normal liver cells L02." (PMID 36157234, 2022). "Therefore, the lncRNA TINCR/miR-375/ATG7 signaling axis could be a novel biological target for the diagnosis and therapy of liver cancer." (PMID 36157234, 2022).
oral squamous cell carcinoma (4 papers, 2019 to 2025). "The lncRNA PLAC2 (also known as TINCR) is transcriptionally activated by H3K27ac modification at the promoter region in oral squamous cell carcinoma (OSCC), and promotes cell growth and metastasis via activating Wnt/β-catenin signaling pathway." (PMID 34690755, 2021).
cardiac hypertrophy (3 papers, 2017 to 2022). "LncRNA TINCR is downregulated in hypertrophic hearts and lentiviral TINCR overexpression attenuates cardiac hypertrophy by interacting with EZH2, a functional enzymatic component of the Polycomb Repressive Complex 2 (PRC2)." (PMID 39086960, 2022). "The present study was aimed to determine the potential role of TINCR in the pathogenesis of cardiac hypertrophy." (PMID 28548932, 2017). "In conclusion, our study revealed that CaMKII is a new target of suppression by EZH2-mediated H3K27me3 and is epigenetically inhibited by TINCR, which will provide a novel therapeutic strategy for cardiac hypertrophy." (PMID 28548932, 2017). "We then carried out in vivo and in vitro experiments to investigate the molecular mechanisms by which TINCR is involved in the regulation of myocardial hypertrophy." (PMID 28548932, 2017). "The present study was designed to determine the potential role of TINCR in the pathogenesis of cardiac hypertrophy." (PMID 28548932, 2017). "The results showed that heart/body ratio, LVPWd, LVPWs, IVSd and IVSs were significantly increased in the TAC group compared to the control group, while TINCR overexpression was found to attenuate cardiac hypertrophy in the TAC mice." (PMID 28548932, 2017). "In conclusion, our findings demonstrated that TINCR could attenuate myocardial hypertrophy by epigenetically silencing of CaMKII, which may provide a novel therapeutic strategy for cardiac hypertrophy." (PMID 28548932, 2017). "Our results showed that enforced expression of TINCR could attenuate cardiac hypertrophy in TAC mice." (PMID 28548932, 2017). "In the present study, our findings suggested that CaMKII was upregulated in hypertrophic myocardium, and it might be epigenetically regulated by TINCR and involved in the pathogenesis of myocardial hypertrophy." (PMID 28548932, 2017). "In this study, we generated a mouse model of cardiac hypertrophy using TAC method and found that lncRNA TINCR was downregulated in the myocardial tissue." (PMID 28548932, 2017). "In the previous study, we established a mouse model of cardiac hypertrophy using transverse aortic constriction (TAC) and found that the expression of long non-coding RNAs TINCR was downregulated in myocardial tissue." (PMID 28548932, 2017).
esophageal squamous cell carcinoma (3 papers, 2017 to 2022). Esophageal squamous cell carcinoma (ESCC) is a type of esophageal carcinoma (EC) that can affect any part of the esophagus, but is usually located in the upper or middle third. "In esophageal squamous cell carcinoma, TINCR was reported to be up-regulated and promote tumorigenesis as well." (PMID 29614984, 2018). "Tissue differentiation-inducing non-protein coding RNA (TINCR) was previously reported to be upregulated in esophageal squamous cell carcinoma and might facilitate its development through an association with CLND7 and ANAX1." (PMID 28225791, 2017).